MYOT (myotilin)
Diseases named in the same sentence as MYOT in open-access papers (continued):
Sharing a sentence is not in itself a finding about the gene and the disease.
myopathy (continued). "Other proteins of cytoskeleton such as Myosin, Tubulin, Myotilin, Vimentin, Zyxin, Nexilin, and Troponin were found to be differentially expressed in GNE myopathy muscle biopsy samples." (PMID 41339784, 2025). "The reported pathological features in all HSPB8-related myopathies have been similar: dystrophic changes and MFM pathology with protein aggregates (desmin, myotilin, CRYAB, dystrophin, HSPB8, DNAJB6, myotilin, BAG3, TDP-43, and ubiquitin) and rimmed vacuoles." (PMID 32093037, 2020). "Next‐generation sequencing with a gene panel including distal and myofibrillar myopathies showed a novel heterozygous interstitial duplication of the whole MYOT gene not reported so far in control populations (Database of Genomic Variants)." (PMID 39757377, 2025). "In addition, investigations should be carried out on more hereditary myopathies candidate genes, including α-B crystalline (CRYAB), dystrophin (DMD) and myotilin (MYOT) in the future." (PMID 24948216, 2014). "The linkage intervals included the myopathy genes MYOT and CRYAB, but neither of these contained coding or splice site mutations by Sanger sequencing." (PMID 22371254, 2012). "Likewise, MYOTILIN (encoded by MYOT) serves as a structural component of the sarcomere, and MYOT mutations have been identified as the most common underlying cause of Myopathy, Myofibrillar, 3 (MFM3; OMIM: 609200) with no satellite cell dysfunction reported." (PMID 34740639, 2022). "Specificity was low considering overall pattern analysis, however, was high for some diseases, such as MYOT, MYH7, GNE-related myopathy, and TTN-HMERF However the low prevalence of these diseases and the limited number of cases may have overestimated these values." (PMID 29997562, 2018).
cancer (2 papers, 2016 to 2017). A tumor composed of atypical neoplastic, often pleomorphic cells that invade other tissues. "Three other genes, IFIH1, MYOT and SAMD4A, that were found to be overexpressed in the Top-resistant cell lines were not previously reported to be related to drug resistance or even to any cancer." (PMID 28611294, 2017).
tumor (2 papers, 2013 to 2025). "Furthermore, Disease Gene Network analysis highlighted fibroid tumor disease as the top enriched condition in both MyoF vs. MyoN and MyoT vs. MyoN comparisons, reinforcing the functional relevance of these transcriptomic changes to fibroid biology." (PMID 40474053, 2025). "Notably, fibroid tumor disease ranked as the top enriched disease in both MyoF vs. MyoN and MyoT vs. MyoN comparisons." (PMID 40474053, 2025). "Disease ontology analysis of MyoT vs. MyoN revealed enrichment of the fibroid tumor gene set." (PMID 40474053, 2025). "Moreover, small GTPase subfamily Rab-like 3 (Rabl3) and actin-binding protein Myotilin, promote motility, tumor cell survival." (PMID 23950931, 2013).
cardiac diseases (1 paper, 2011). "Apart from tumors, Ankrd2 could be linked to dystrophies and cardiac diseases since some proteins from the FATZ (myozenin/calsarcin), myotilin and Enigma families are differentially expressed in Ankrd2 silenced myotubes." (PMID 22016770, 2011).
infection (1 paper, 2017). The state of being infected such as from the introduction of a foreign agent such as serum, vaccine, antigenic substance or organism. "After retesting shRNAs targeting the top screen candidates, we found that infection with shRNAs targeting four of these genes (CDKN1A, MTOR, MYOT, and UBE2E1) resulted in a consistent bypass of OSKM-induced senescence." (PMID 29138277, 2017).
skeletal muscle disorder (1 paper, 2011). A disease involving the skeletal muscle tissue. "DRMs are a growing class of skeletal muscle disorders caused by mutations in desmin, αB-crystallin, Z-band alternatively spliced PDZ motif, myotilin, filamin C, and Bag3." (PMID 21445271, 2011).
MYOT also shares sentences with these, for which no sentence is quoted: limb girdle muscular dystrophy type 1a (3 papers); Alzheimer disease (2); filaminopathy (2); colon tumor (1); congenital muscular dystrophy (1); congenital myasthenic syndrome (1); congenital myopathy (1); congestive heart failure (1); dermatomyositis (1); genetic disorder (1); malaria (1); multiple sclerosis (1); muscle disorders (1); Myotonia (1); neurodegenerative disease (1); Norum disease (1); Respiratory insufficiency (1).